ERBB2 (erb-b2 receptor tyrosine kinase 2)
Diseases named in the same sentence as ERBB2 in open-access papers (continued):
Sharing a sentence is not in itself a finding about the gene and the disease.
pancreatic cancer (continued). "The expression level of the EGFR receptor in PDAC is about 30 to 90 percent, while erbB-2 expression is about 10 to 80 percent in pancreatic cancer tissue samples." (PMID 36013144, 2022). "After confirmation of the binding between miR-488 and ERBB2, the specific effects of ERBB2 upon pancreatic tumor cell lines were further investigated." (PMID 35343383, 2022). "Similar to miR-488 overexpression, ERBB2 knockdown in pancreatic cancer cells attenuated the cancer cell malignancy by inhibiting the cell viability, promoting cell apoptosis, and eliciting cell cycle G2/M-phase arrest." (PMID 35343383, 2022). "In pancreatic cancer tissues, ERBB2 expression was significantly upregulated than that within normal control tissues." (PMID 35343383, 2022). "The protein expression of ErbB2 is upregulated between 7 to 61% of patients with pancreatic cancer and about 2 to 24% of patients show ErbB2 gene amplification." (PMID 35448172, 2022). "The specific invitro effects of ERBB2 and the dynamic effects of miR-488 and ERBB2 on pancreatic cancer cell phenotypes were examined." (PMID 35343383, 2022). "Our study has provided a direct association between pancreatic cancer survival and the overexpression of EGFR, beta-catenin, cyclin D1, CDK4, and ErbB2." (PMID 35448172, 2022). "Since miR-488 directly targets ERBB2, the dynamic effects of miR-488 and ERBB2 on pancreatic tumor cell lines were subsequently examined." (PMID 35343383, 2022). "Notwithstanding, the role of ErbB2 in pancreatic cancer prognosis is well defined, and its therapeutical implications are not as promising as expected." (PMID 35448172, 2022). "More importantly, ERBB2 knockdown significantly reversed the roles of miR-488 inhibition in pancreatic tumor cell lines, indicating that miR-488 exerts atumor-suppressive effect on pancreatic carcinoma through targeting ERBB2 to modulate the cancer cell cycle." (PMID 35343383, 2022). "Pro-oncogenic mutations such as in tumor suppressor p16INK4a and ErbB2 have also been noted in both PSC and pancreatic cancer." (PMID 38347877, 2022). "A NF-κB/miR-488/ERBB2 axis modulating pancreatic cancer cell malignancy and tumor growth through cell cycle signaling is therefore conclusively demonstrated." (PMID 35343383, 2022). "Mechanistic investigations revealed that VPA treatment resulted in simultaneous significant down-regulation of EGFR, ErbB2, and ErbB3 in pancreatic cancer cells likely via induction of ErbB family members-targeting microRNAs." (PMID 30961642, 2019). "In our attempt to determine the underlying mechanisms of anti-pancreatic cancer activity of VPA, the possible effect of VPA on expression of EGFR, ErbB2 and ErbB3 was investigated." (PMID 30961642, 2019). "We demonstrated that VPA inhibits proliferation/survival of pancreatic cancer cells as well as induces caspase-dependent apoptosis selectively in EGFR/ErbB2/ErbB3-coexpressing pancreatic cancer within its clinically achievable range." (PMID 30961642, 2019). "Mechanistically, VPA treatment was evidenced to result in significant inactivation of Akt and MAPK signalings via simultaneous down-regulation of EGFR, ErbB2, as well as ErbB3 in pancreatic cancer cells." (PMID 30961642, 2019). "Collectively, our results demonstrate that VPA selectively exerts anti-tumor activity in vitro through induction of growth inhibition as well as apoptosis in the EGFR/ErbB2/ErbB3-coexpressing pancreatic cancer cells." (PMID 30961642, 2019). "In fact, several studies had showed that combined targeting of EGFR and ErbB2 did result in enhanced efficacy in treatment of pancreatic cancer." (PMID 30961642, 2019). "Significantly reduced VPA-induced apoptosis in pancreatic cancer cells with exogenous expression of either ErbB2 or ErbB3 were further demonstrated by a specific apoptotic ELISA assay." (PMID 30961642, 2019).
pancreatic cancer (continued). "In this context, the inhibition of the oncogenic activity by developing MUC4β-ErbB2 protein-protein interaction (PPI) modulators appears as a promising therapeutic alternative in pancreatic cancer." (PMID 31723153, 2019). "In our attempt to seek novel strategy to treat pancreatic cancer, we found that VPA exhibits a promising anti-tumor activity selectively against EGFR/ErbB2/ErbB3-coexpressing pancreatic cancer." (PMID 30961642, 2019). "ErbB2 additionally modulates the resistance of pancreatic cancer cells to the chemotherapeutic gemcitabine." (PMID 31608239, 2019). "VPA-induced apoptosis in the EGFR/ErbB2/ErbB3-coexpressing pancreatic cancer cells was also confirmed by flow cytometry analysis." (PMID 30961642, 2019). "Presently, we show the advantage of delivering HDACi to both ErbB2+ colon and pancreatic carcinomas by the ADC ST8176AA1." (PMID 32039017, 2019). "MUC4 and its membrane partner the oncogenic receptor ErbB2 interact physically in pancreatic cancer cells, and silencing of ErbB2 results in enhanced gemcitabine sensitivity via upregulation of hCNT1 and hCNT3 expression." (PMID 29144412, 2017). "In vivo, PEAK1-dependent kindles induced by oncogenic KRas amplify the loop between SRC, PEAK1, and ERBB2 drive pancreatic cancer." (PMID 28871116, 2017). "In ERBB2/EGFR-positive pancreatic cancer cell lines lapatinib has limited efficacy due to k-ras mutations." (PMID 25596742, 2015). "We also explored the potential mechanisms underlying the tumor suppression role of YY1 and found that YY1 suppresses invasion and metastasis of pancreatic cancer cells by downregulating MMP10 in a MUC4/ErbB2/p38/MEF2C-dependent mechanism." (PMID 24884523, 2014). "Previous studies showed that MUC4 and ErbB2 interact physically and transduce signals intracellularly, thus promoting the migratory and metastatic potential of pancreatic cancer cells." (PMID 24884523, 2014). "YY1 suppresses invasion and metastasis of pancreatic cancer cells by downregulating MMP10 in a MUC4/ErbB2/p38/MEF2C-dependent mechanism." (PMID 24884523, 2014). "The YY1 high-level overexpression suppresses invasion and metastasis of pancreatic cancer cells by downregulating MMP10 via a MUC4/ErbB2/p38/MEF2C-dependent mechanism." (PMID 24884523, 2014). "The mucin MUC4 and its membrane partner the ErbB2 oncogenic receptor are potential interacting partners in human pancreatic tumour development." (PMID 22393391, 2012). "Altogether, these results indicate that MUC4 and ErbB2 physically interact in CAPAN-2 pancreatic cancer cells via MUC4EGF3+1+2 region that contains the three EGF-like domains." (PMID 22393391, 2012). "Our data also suggests a role in pancreatic tumour growth for ErbB2, while MUC4 is involved in both tumour growth and dissemination." (PMID 22393391, 2012). "Via its control of the balance between relative expression levels of Muc4 and ErbB2, Pea3 is thought to promote pancreatic cancer cell differentiation." (PMID 20949099, 2010). "Pea3 is a positive regulator of Muc4 expression in pancreatic cancer cells, whilst also acting as a negative regulator of ErbB2." (PMID 20949099, 2010). "Recently, we have also shown that in pancreatic cancer cells MUC4 interacts with ErbB2 and stabilizes its localization on the cell membrane." (PMID 18781152, 2008). "shRNA-mediated knock-down of MUC4 in pancreatic cancer cells showed a decrease in the total levels and phosphorylated form of ErbB2 protein (at Tyr1248) and was shown that overexpression of MUC4 plays a crucial role in stabilising ErbB2." (PMID 18781152, 2008).
pancreatic cancer (continued). "MUC4 also interacts with ErbB2, a growth factor receptor, stabilizes it at the cell surface and hence has an important function in modulating ErbB2-mediated oncogenic signaling in pancreatic cancer cells." (PMID 18781152, 2008). "We compared ERBB2 gene copy number, p185c-erbB-2 and mRNA levels with AP-2 levels in several ovary, prostate, colon and pancreas cancer cells." (PMID 12942124, 2003). "ERBIN, a scaffold protein that modulates ERBB2 signalling, may further contribute to pancreatic cancer progression." (PMID 40952239, 2025). "In the future, NGS will have a greater impact on CDM, as targeted treatment options for CCA and pancreatic carcinoma expand, including US Food and Drug Administration-approved options for mutations in theFGFRpathway,IDH1,ERBB2,BRCA1/2, and microsatellite-instable tumors." (PMID 40932825, 2025). "In patients who underwent pancreatoduodenectomy for pancreatic cancer (PC), pro-inflammatory genes and a tumor marker, erythroblastic oncogene 2 (ErbB2) in the epidermal growth factor receptor family were analyzed in the pancreatic tissue at the cut surface of the normal pancreas using qRT-PCR." (PMID 38533139, 2024). "The upregulated ErbB2 gene in the unaffected pancreatic tissue of pancreatic cancer patients, when compared to controls, indicates that the remaining pancreas may have the capacity to cause cancer." (PMID 38533139, 2024). "ErbB2 overexpression has been observed in 0-82% of pancreatic cancer cases." (PMID 38559560, 2024). "In one study, only 64% of pancreatic tumors graded as IHC 3+ exhibited ERBB2 amplification." (PMID 37119523, 2023). "Because EGFR and ERBB2 play an important role in PDAC we decided to crossbreed the Trap animals into the well‐established KRASG12D/+ PDAC mouse model to investigate the function of our decoy molecule in pancreatic cancer." (PMID 37341059, 2023). "Here, we showed that ErbB2/ErbB3 heterodimer could have essential roles in this process when iPSCs treat with CM from pancreatic cancer cells." (PMID 35177646, 2022). "In summary, in pancreatic tumor cells, ERBB2 also plays an oncogenic role." (PMID 35343383, 2022). "Finally, the predicted binding between NF-κB and miR-488 was determined, and the dynamic effects of NF-κB inhibitor and miR-488 upon ERBB2 expression and pancreatic cancer cell phenotype were examined." (PMID 35343383, 2022). "•IPO7 facilitated the malignant phenotype of pancreatic cancer cells by up-regulating ERBB2." (PMID 35588577, 2022). "Anovel NF-κB/miR-488/ERBB2 axis that might affect pancreatic cancer development through the modulation of the cancer cell cycle was conclusively identified." (PMID 35343383, 2022). "Thus, an NF-κB/miR-488/ERBB2 axis modulating pancreatic cancer cell malignancy and tumor growth through cell cycle signaling was conclusively demonstrated." (PMID 35343383, 2022). "YY1 could suppress the invasion and proliferation of pancreatic cancer cells through MUC4/ErbB2/p38/mef2cMEF2C-dependent mechanism." (PMID 35359580, 2022). "The ERBB2 mRNA level was observably higher in the bladder, brain and CNS, breast, and pancreatic cancer tissues and signally lower in the colorectal, esophageal, head and neck, kidney, lung, lymphoma, and sarcoma cancers compared with the corresponding normal tissues." (PMID 33732282, 2021). "Some pancreatic cancer patients are with ERBB2 amplification." (PMID 32950968, 2020). "Finally, our assay identified 0.20–8.41% of tumors across 15 cancer types as ERBB2-high, including gastric and esophagus adenocarcinomas, urothelial carcinoma, cervical squamous carcinoma and pancreatic cancer." (PMID 32674482, 2020). "Therefore, EGFR and ERBB2 differentially impact ERBB signaling during pancreatic cancer tumorigenesis, highlighting the need to consider patient’s specific characteristics of ERBB signaling to optimize therapeutic treatment." (PMID 32251323, 2020).
pancreatic cancer (continued). "HER2 (or Erbb2) is a 185 KDa transmembrane glycoprotein known to be overexpressed in a variety of cancers including breast, ovarian, cervical, colon, endometrial, esophageal, lung, and pancreatic cancers." (PMID 32039018, 2019). "A report indicated that YY1 could suppress invasion and metastasis by downregulating MMP10 in a MUC4/ErbB2/p38/MEF2C-dependent manner in pancreatic cancer cells, suggesting MEF2C phosphorylation is required for MMP10 expression." (PMID 30836712, 2019). "Thus, VPA treatment simultaneously down-regulates expression of EGFR, ErbB2, and ErbB3 in the ErbB family members-coexpressing pancreatic cancer cells, which in turn results in induction of cell growth inhibition as well as apoptosis." (PMID 30961642, 2019). "Thus, our in vivo data further confirmed that VPA exhibits anti-tumor activity selectively against EGFR/ErbB2/ErbB3-coexpressing pancreatic cancer likely via induction of miRNAs that target the erbB mRNAs." (PMID 30961642, 2019). "Amplification of the ERBB2 gene in pancreatic cancer has also been observed by ctDNA analysis." (PMID 31608239, 2019). "We reported here that VPA-induced simultaneous down-regulation of EGFR, ErbB2, and ErbB3 in pancreatic cancer cells could be mainly attributed to induction of ErbB family members-targeting miRNAs both in vitro and in vivo." (PMID 30961642, 2019). "In addition to EGFR and ErbB2, their kin ErbB3 is emerging as an attractive druggable target in pancreatic cancer." (PMID 30961642, 2019). "Mechanistic investigations revealed that VPA simultaneously down-regulates EGFR, ErbB2 and ErbB3 likely via induction of several critical miRNAs in pancreatic cancer cells, and thereby results in inactivation of downstream Akt and MAPK signaling pathways and induces cell apoptosis and growth arrest." (PMID 30961642, 2019). "We had also previously showed that the human mucin MUC4 forms a complex at the membrane with the oncogenic receptor ErbB2 and that loss of MUC4 in pancreatic cancer cells led to an increased sensitivity to gemcitabine and an increased expression of hCNT1 correlated to cell survival." (PMID 25890497, 2015). "The membrane-bound mucin, MUC4, which is expressed as early as PanIN-1A but is not expressed in the healthy pancreas, and its membrane partner, the oncogenic receptor ErbB2, which is frequently overexpressed in pancreatic cancer as well as in PanINs, represent promising therapeutic targets." (PMID 24884523, 2014). "Previous studies showed that MUC4 and ErbB2 might interact physically and transduce signals intracellularly, thus promoting the migratory and metastatic potential of pancreatic cancer cells." (PMID 24884523, 2014). "MUC4 has shown to interact with HER2/ErbB2 in ovarian and pancreatic cancers." (PMID 25261375, 2014). "In the present work, we undertook to identify the intracellular signalling pathways under the control of either ErbB2 or MUC4 in the same cellular model of pancreatic cancer to test this hypothesis." (PMID 22393391, 2012). "Regarding ErbB2, only one recent study in another pancreatic cancer cell model has shown that ErbB2 may be involved in the properties of pancreatic cancer cells." (PMID 22393391, 2012). "Also, NF-κB/miR-488/ERBB2 axis is reported to modulate the pancreatic tumor growth." (PMID 38533139, 2024). "Hence, it could be concluded that either protein expression or gene heterogeneity involving ErbB2 is a significant prognostic marker in pancreatic cancer." (PMID 35448172, 2022). "However, the usefulness of ErbB2 in the prognosis of pancreatic cancer is still controversial." (PMID 35448172, 2022). "Hbegf-Egfr/Erbb2 is one of the main contributors to EGF signaling, and EGFR-activated myo-CAFs can promote pancreatic cancer metastasis." (PMID 40538442, 2025). "This is a potential limitation, particularly if there is discordance between ERBB2 copy number and HER2 overexpression in UBC, pancreatic cancer, or cholangiocarcinoma." (PMID 37119523, 2023).
pancreatic cancer (continued). "By employing CRISPR/Cas9 gene‐editing technology we successfully deleted EGFR, ERBB2, ERBB3, and ERBB4, respectively, in the human pancreatic cancer cell line Panc‐1." (PMID 37341059, 2023). "Consistently, ERBB2 knockdown also decreased cyclin A, cyclin B, CDK1, and CDK2 protein contents in both pancreatic tumor cells." (PMID 35343383, 2022). "The current results indicate that AKT1, CDKN2A, ERBB2, and IL6 are the common protein core of liver and pancreatic cancers, and STAT3, CASP3, NOTCH1, and CTNNB1 are possible differential proteins that discriminate these cancers." (PMID 35154607, 2021). "AKT1, CDKN2A, ERBB2, and IL6 are common protein core of liver and pancreatic cancers, while STAT3, CASP3, NOTCH1, and CTNNB1 are possible differential proteins to discriminate these cancers." (PMID 35154607, 2021). "The current findings indicate that AKT1, CDKN2A, ERBB2, and IL6 are the critical common hubs related to promoting both liver and pancreatic cancers." (PMID 35154607, 2021). "Next to that, in vitro and in vivo data in pancreatic cancer show that silencing of MUC4 expression results in altered tumor cell behavior, decreased growth, decreased ErbB2 expression and a marked reduction in metastatic incidence." (PMID 31723153, 2019). "As compared to other pancreatic carcinoma cell lines, HPDE cells express relatively lower levels of EGFR, erbB2, TGF-α, HGFR, VEGF and KGF." (PMID 25373319, 2014). "In ERBB2-STAT, these genes are involved in pancreatic cancer and signal transduction pathways; the correlation between the activation of ERBB2 and STAT3 has been observed in many human tumors." (PMID 23940583, 2013). "Our results show that ErbB2 and MUC4, which interact physically, activate different intracellular signalling pathways to regulate biological properties of CAPAN-2 pancreatic cancer cells." (PMID 22393391, 2012). "Altogether, these results indicate that both ErbB2 and MUC4 play a role in pancreatic tumour growth in vivo." (PMID 22393391, 2012). "EGF-R, erbB-2 and related members of the EGF receptor tyrosine kinases are also over expressed in pancreatic cancer." (PMID 15801978, 2005). "In order to ascertain the expression of inflammatory markers and Erythroblastic Oncogene B (ErbB2) in the non-affected pancreas in patients with pancreatic cancer, a case-control study was carried out." (PMID 38533139, 2024). "However, there is a discordance between HER2 overexpression and ERBB2 gene amplification in pancreatic cancer." (PMID 37119523, 2023). "ERBB2 knockdown in MIA PaCa-2 and PANC-1 cell lines suppressed, however, miR-488 inhibition enhanced the cancer cell cytological malignant behavior; the effects of miR-488 inhibition on pancreatic cancer cells were significantly reversed by ERBB2 knockdown." (PMID 35343383, 2022). "ERBB2 knockdown in MIA PaCa-2 and PANC-1 cell lines suppressed, but miR-488 inhibition enhanced the cancer cell biological malignant behavior; the effects of miR-488 inhibition on pancreatic cancer cells were significantly reversed by ERBB2 knockdown." (PMID 35343383, 2022). "Moreover, results in this experiment show remarkable synergistic effects observed in pancreatic cancer cells treated with selective STAT3 inhibitors, an EGFR/ErbB2 inhibitor, and a HIF-1α inhibitor." (PMID 33544704, 2021). "Among all subfamilies of RTKs, the ErbB family members consisting of the epidermal growth factor receptor EGFR (ErbB1), HER2 (ErbB2), HER3 (ErbB3), and HER4 (ErbB4) play important role in the initiation and maintenance of a variety of human cancers, including pancreatic cancer." (PMID 30961642, 2019).